SCAF1 (SR-related CTD associated factor 1)
Description:
May function in pre-mRNA splicing.
Synonyms: SR-A1; SRA1; FLJ00034
Tractability: PROTAC: UniProt records ubiquitination sites on it; ubiquitination databases record sites on it; its protein half-life has been measured.
Gene: Protein-coding gene on chromosome 19 (49,640,488 to 49,658,649, forward strand). Ensembl gene ENSG00000126461.
Subcellular location: Nucleus
Subcellular location (Human Protein Atlas): Nucleoplasm; Cytosol
Gene Ontology:
Molecular function: protein binding; RNA polymerase II C-terminal domain binding; protein domain specific binding
Biological process: mRNA processing; transcription by RNA polymerase II
Cellular component: nucleus
Genetic constraint (gnomAD): Loss-of-function variants: 28 observed, 69.39 expected, observed/expected ratio (o/e) 0.4, 90% interval 0.3 to 0.55. The synonymous counts are far from expectation, so gnomAD's model fits this gene poorly and the ratio says little. Missense variants: 1,845 observed, 1,550.1 expected, observed/expected ratio (o/e) 1.19, 90% interval 1.14 to 1.24. Synonymous variants: 1,004 observed, 713.9 expected, observed/expected ratio (o/e) 1.41, 90% interval 1.34 to 1.48.
Homologues: Orthologues: dog SCAF1 (95% identical), chimpanzee SCAF1 (94% identical), pig SCAF1 (92% identical), macaque SCAF1 (89% identical), mouse Scaf1 (85% identical), rat Scaf1 (85% identical), guinea pig SCAF1 (80% identical), tropical clawed frog scaf1 (41% identical), zebrafish scaf1 (31% identical), Drosophila melanogaster CG2926 (18% identical). Paralogues in human: PHRF1 (20% identical), SCAF11 (13% identical).
Diseases named in the same sentence as SCAF1 in open-access papers:
SCAF1 is named in the same sentence as 17 diseases in open-access papers, as found by Europe PMC text mining. Sharing a sentence is not in itself a finding about the gene and the disease. The quoted sentences say what the papers report.
pancreatic cancer (3 papers, 2022 to 2024). "Lastly, we set out to elucidate how Usp15 and Scaf1 regulate the response of pancreatic cancer cells to PARP inhibition." (PMID 38902237, 2024). "Together, these data demonstrate the tumor suppressive function of USP15 and SCAF1 in pancreatic cancer by modulating several important signaling pathways and that loss of USP15 and SCAF1 sensitizes to Gemcitabine and Olaparib." (PMID 38902237, 2024). "In line with the previous screen, Cdkn2a was the top-scoring gene followed by Rnf43 and the newly identified genes, Usp15 and Scaf1, further supporting their function as strong suppressors of pancreatic cancer in KC mice." (PMID 38902237, 2024). "Perturbation of electron transfer efficiency by downregulating SCAF1 specifically affects hypoxic pancreatic cancer, breast and endometrial cancer proliferation, metabolism, and in vivo tumor growth." (PMID 38769295, 2024). "Here, we perform somatic CRISPR/Cas9 mutagenesis screens to assess the transforming potential of 125 recurrently mutated pancreatic cancer genes, which revealed USP15 and SCAF1 as pancreatic tumor suppressors." (PMID 38902237, 2024). "The role of COX7A2L (SCAF1) in promoting SC assembly has been demonstrated in breast cancer, pancreatic cancer, normal mouse tissue and bovine heart mitochondria." (PMID 35478774, 2022). "Notably, USP15 and SCAF1 alterations are observed in 31% of pancreatic cancer patients." (PMID 38902237, 2024). "Further functional studies will be required to explore the relevance of SCAF1 and aberrant polyadenylation in USP15 processing and pancreatic cancer." (PMID 38902237, 2024).
breast carcinoma (2 papers, 2022 to 2024). "Remarkably, proteins prominently expressed in NmFMC compared with other groups, such as F13A1, CENPF, INSR, SCAF1 and PDK1, have been implicated in human breast cancer, further supporting the potential use of FMC as a model for studying human breast cancer." (PMID 38951817, 2024). "Differential splicing of INSR occurs more commonly in human breast cancer than in non-tumor breast tissues, and SCAF1 has been proposed as a cancer prognostic biomarker." (PMID 38951817, 2024).
endometrial cancer (2 papers, 2019 to 2024). Primary or metastatic malignant neoplasm involving the endometrium (mucous membrane that lines the endometrial cavity). "Here we show that a stabilizing factor for mitochondrial supercomplex assembly, COX7RP/COX7A2L/SCAF1, is abundantly expressed in clinical breast and endometrial cancers." (PMID 31511525, 2019).
Cognitive impairment (1 paper, 2022). Abnormal cognition is characterized by deficits in thinking, reasoning, or remembering. "Autistic individuals with LoF variants in the four moderate-risk genes (NAV3, ITSN1, SCAF1 and HNRNPUL2; n = 95) have less cognitive impairment than 129 autistic individuals with LoF variants in highly penetrant genes (CHD8, SCN2A, ADNP, FOXP1 and SHANK3) (59% vs 88%, P = 1.9 × 10−6)." (PMID 35982159, 2022).
gastric cancer (1 paper, 2024). A primary or metastatic malignant neoplasm involving the stomach. "We demonstrate that targeting SOX13/SCAF1 inhibits respiratory chain supercomplexes (SCs) assembly to overcome ferroptosis-mediated anticancer therapy resistance in gastric cancer." (PMID 38769295, 2024). "Here, the authors demonstrate that SOX13 promotes ferroptosis-resistance via transactivation of SCAF1, identifying SOX13 as a targeted therapeutic vulnerability in gastric cancer." (PMID 38769295, 2024).
Intellectual disability (1 paper, 2022). "The absence of intellectual disability is also observed in other genes (for example, SCAF1, HNRNPUL2, GIGYF1, KDM5B and KMT2C) with substantial contribution from rare inherited variants and modest effect size." (PMID 35982159, 2022).
lung adenocarcinoma (1 paper, 2025). A carcinoma that arises from the lung and is characterized by the presence of malignant glandular epithelial cells. "In the TCGA lung adenocarcinoma cohort, PPP2R1A expression demonstrated significant positively correlated with PRPF31 (R = 0.72), SCAF1 (R = 0.72), and PTOV1 (R = 0.71)." (PMID 41409293, 2025).
malnutrition (1 paper, 2020). Inadequate nutrition resulting from poor diet, malabsorption, or abnormal nutrient distribution. "The lack of SC formation due to Scaf1 ablation reduces the efficiency of conversion of nutrients into energy, mimicking some features associated with malnutrition in zebrafish 24, such as impaired growth and fertility." (PMID 32496654, 2020).
muscular dystrophy (1 paper, 2022). Muscular dystrophy (MD) refers to a group of more than 30 genetic diseases characterized by progressive weakness and degeneration of the skeletal muscles that control movement. "Three notable exceptions were i) SR-A1 [a.k.a, SCAF1, Serine/Arginine Rich (SR)-related C-terminal domain-associated factor 1] a poorly characterized SR family protein, ii) MBNL1 (Muscleblind-like 1), a RBP known for its role in muscular dystrophy and, (iii) RBM39." (PMID 36477312, 2022).
tumor (8 papers, 2020 to 2026). "Single-cell and spatial transcriptomic analyses further suggested that SCAF1 was mainly associated with endothelial and immune-related features of the tumour microenvironment." (PMID 42178613, 2026). "Here, using in vivo CRISPR screens, the authors integrate human cancer genomics and mouse models, identifying that loss of USP15 or SCAF1 accelerates tumor development and leads to reduced inflammatory responses and increased sensitivity to PARP inhibition and Gemcitabine." (PMID 38902237, 2024). "Together these data indicate that the short isoform has no tumor suppressive functions or alters the response to PARP inhibition and that Scaf1’s tumor suppressive function is at least in part routed by regulating the expression of full-length Usp15." (PMID 38902237, 2024). "In another cohort of patients who received cisplatin-based neoadjuvant chemotherapy (n = 52) 10, high coexpression of SOX13/SCAF1 was positively correlated with poor response to chemotherapy as evidenced by higher tumor regression grades (TRG)." (PMID 38769295, 2024). "First, we validated the tumor suppressive function of Scaf1 by injecting KC mice individually with one library or one newly designed sgRNA." (PMID 38902237, 2024). "We also show that SCAF1 deficiency partly rescues RAD51 loading in cells lacking the BRCA1 tumor suppressor." (PMID 38880245, 2024). "Nonetheless, when considering genes that may encode novel therapeutic targets of both tumour insulin-expressing cell populations, the small number of genes ubiquitously expressed and upregulated in both clusters included COX7A2L (also known as COX7RP and SCAF1), with a mean 27-fold upregulation." (PMID 40438247, 2025). "These candidates included well-known PDAC tumor suppressor genes, such as Cdkn2a23, Rnf4324, Fbxw725 or NF226, as well as genes with poorly understood function, such as Usp15 and Scaf1." (PMID 38902237, 2024). "SCAF1 has been reported to modulate the level of NADPH39, and NADPH could boost the antioxidant defense in tumor cells by supporting the biosynthesis of GSH, Trx, and CoQ10-H2 to rescue them from ferroptosis." (PMID 38769295, 2024).
cancer (3 papers, 2024). A tumor composed of atypical neoplastic, often pleomorphic cells that invade other tissues. "The transcript level of SOX13 positively correlates with that of SCAF1 in multiple cancers, including GC, based on the databases TIMER and GEPIA." (PMID 38769295, 2024).
SCAF1 also shares sentences with these, for which no sentence is quoted: acute kidney injury (1 paper); autism (1); diabetic kidney disease (1); pancreatic ductal adenocarcinoma (1); schizophrenia (1); scrub typhus (1).